ADRM1 (ADRM1 26S proteasome ubiquitin receptor)
Diseases named in the same sentence as ADRM1 in open-access papers (continued):
Sharing a sentence is not in itself a finding about the gene and the disease.
idiopathic pulmonary fibrosis (1 paper, 2019). Idiopathic pulmonary fibrosis (IPF) is a nonneoplastic pulmonary disease that is characterized by the formation of scar tissue within the lungs in the absence of any known cause. "It has been reported that Adrm1 is downregulated in ageing-associated idiopathic pulmonary fibrosis." (PMID 30770755, 2019).
invasive carcinoma (1 paper, 2017). A carcinoma that is not confined to the epithelium, and has spread to the surrounding stroma. "ADRM1 mRNA levels in matched invasive carcinoma on same slides were considered to be a similar to those in adjacent STIC." (PMID 28784174, 2017).
lung carcinoma (1 paper, 2023). "Exosomal circ-ADRM1 from lung cancer cells (A549 and PC-9 cells) can enhance the M2 polarization of TAMs, which can promote lung cancer cell migration and invasion." (PMID 36979471, 2023). "Compared to normal cells, the expression of circ-ADRM1 is up-regulated in lung cancer cells." (PMID 36979471, 2023).
meningioma (1 paper, 2020). A generally slow growing tumor attached to the dura mater. "Grade-wise comparisons on MGI (benign) vs MGII (atypical) meningiomas revealed prominent involvement of TIMM50, SEC23A, MTAP, RPS23, and ADRM1 based on the concordance analysis of highly ranked features from across 20 Machine Learning randomized iterations obtained via the methods of the Ball group." (PMID 32974197, 2020).
paraganglioma (1 paper, 2023). A benign or malignant neoplasm arising from paraganglia located along the sympathetic or parasympathetic nerves. "ADRM1 was highly expressed in many cancers than counterpart normal tissues in both unpaired and paired samples, except kidney chromophobe, pheochromocytoma, and paraganglioma." (PMID 37684377, 2023).
cancer (27 papers, 2010 to 2025). A tumor composed of atypical neoplastic, often pleomorphic cells that invade other tissues. "With engagement in the Ub proteasome pathway that regulates a broad range of physiological functions, ADRM1 is implicated in multitudinous cellular processes such as cell growth, migration, survival and development, particularly in cancer cells." (PMID 32811556, 2020). "Aberrant expression of ADRM1 is associated with a variety of cancers." (PMID 36335317, 2022). "In addition, ADRM1 loss can have a marked effect on viability in a subset of cancer lines." (PMID 35735670, 2022). "Importantly, ADRM1/RPN13 has already been implicated as a potential target for cancer therapy." (PMID 34572038, 2021). "Of these genes, we found Sh3kbp1, Frmd5 and Adrm1 (nos 16–18) to be upregulated in both treatments, and they are described in the literature to be involved in cancer prevention." (PMID 40275631, 2025). "According to our findings, ADRM1 plays a role in the migration, survival, and proliferation of cancer cells." (PMID 41144480, 2025). "Recent studies have shown that ADRM1 plays crucial roles in the onset and progression of numerous human cancers." (PMID 38890391, 2024). "In RNAi screens, this analysis classified S5A as being essential in half of the cancer cell lines tested, while ADRM1 was scored as being essential in very few cell lines." (PMID 35735670, 2022). "In CRISPR screens, S5A was classified as essential in almost all cancer cell lines employed, while ADRM1 was scored as being essential in around 20% of lines." (PMID 35735670, 2022). "For example, several groups have demonstrated the potential for targeting adhesion-regulating molecule 1 (ADRM1/hRPN13) in cancer therapy and bortezomib resistance." (PMID 36498916, 2022). "Given the association of amounting ADRM1 expression with the onset and progression of cancers, ADRM1 has been defined as a potential predictive and therapeutic target for clinical therapy." (PMID 32811556, 2020). "Fifty-six genes were identified as significant genes and included cancer-associated genes such as BOK, FANCD2, ADRM1 and EGLN1." (PMID 32437477, 2020). "Using R Software, we initially examined ADRM1 expression in various types of cancer." (PMID 38890391, 2024). "We performed a survival analysis of ADRM1 in the cancer types of interest." (PMID 38890391, 2024). "ADRM1 was predominantly localized within the nuclei of cancer cells." (PMID 37684377, 2023). "Specifically, inhibiting ADRM1 would suppress cancer cells growth in vitro." (PMID 37684377, 2023). "Small molecule inhibitors of ADRM1 are being developed for the treatment of cancer." (PMID 35735670, 2022). "We assessed the roles of S5A and ADRM1 in maintaining cancer cell line viability." (PMID 35735670, 2022). "Whether the overexpression of ADRM1 is regulated by transcription factors in cancer requires more research." (PMID 36551532, 2022). "Rpn13 and the deubiquitinating enzyme that it activates, Uch37, have been found to be important for cell cycle progression in cell culture, and increased expression of the gene encoding Rpn13 (ADRM1) has been identified in several forms of cancer." (PMID 32033280, 2020). "Moreover, ADRM1 is a therapeutic target for cancer treatment." (PMID 36551532, 2022). "The specificity of ADRM1 overexpression to developing tumors implies it may be reflect an early response to accommodate an overabundance of misfolded proteins found even in the cancer precursor." (PMID 28784174, 2017). "Proteasome–ubiquitin receptor hRpn13/Adrm1 binds and activates deubiquitinatingenzyme Uch37/UCHL5 and is targeted by bis-benzylidine piperidone RA190, whichrestricts cancer growth in mice xenografts." (PMID 28598414, 2017).
tumor (17 papers, 2010 to 2024). "Meanwhile, these high ADRM1-expressing samples displayed elevated tumor mutation burden scores and stemness indices, implying potential benefits from immunotherapy." (PMID 37684377, 2023). "ADRM1 and FGFR4 were strongly correlated with tumor Stage, and ADRM1 was also associated with distant metastasis." (PMID 34724890, 2021). "Based on the ADRM1 gene, this study analyzed the relationship between ADRM1 expression in many types of tumor tissues and the prognosis of tumor patients." (PMID 38890391, 2024). "To investigate the role of ADRM1 in HCC, we examined the expression of ADRM1 in HCC tissue and Huh-7cell, and tested the relationship between ADRM1 levels and tumor stages and grades of HCC patients." (PMID 38890391, 2024). "It has been reported that ADRM1 can promote tumor invasion and the expression of immune checkpoint proteins, thus promoting its tumor-promoting effects." (PMID 38890391, 2024). "Immunostaining revealed higher protein expression for ADRM1 in most of the tumor tissues of BC patients in both unpaired and paired comparisons." (PMID 37684377, 2023). "Based on the immunostaining intensity for ADRM1 in the tumor tissues, patients were categorized into low ADRM1 group (including patients scored by 0–2) and high ADRM1 group (including patients scored by 3)." (PMID 37684377, 2023). "In tumor microenvironment, samples with the high ADRM1 expression contained statistical higher proportion of CD8 + T cells and Macrophage infiltration." (PMID 37684377, 2023). "Dysfunction of ADRM1 restricts NF-κB translocation from the cytosol to the nucleus and thus blocks NF-κB signalling, which induces tumour cell apoptosis." (PMID 36551532, 2022). "KTN1 knockdown increases the expression of CCDC40, PSMA1, and ADRM1 to mediate tumor suppressor functions in vivo and in vitro." (PMID 34689164, 2021). "ADRM1 was originally identified as ADhesion Regulating Molecule-1 in metastatic tumor cells." (PMID 28784174, 2017). "Predictably, images of the liver and H.E. staining showed that overexpression of SIAH1 inhibited tumor growth and intrahepatic metastasis, and immunohistochemistry was used to analyze the expression of SIAH1, ADRM1, UCHL5, FASN, and FSCN1." (PMID 39075049, 2024). "In our previous study, we found that ADRM1 was highly expressed in HCC and was closely related to tumor immune and immune checkpoint levels in HCC." (PMID 38890391, 2024). "The results showed that IL2RA, DNMT3B, ADRM1, and NRIP1 were highly expressed in tumor tissue compared to normal tissue, while ALDH2, NYNRIN, LSP1, and CALCRL were the opposite." (PMID 38322112, 2024). "Previous studies have reported that ADRM1 is upregulated and promotes cell growth in CRC, while there have been few studies on the role of PRPF6 in tumour proliferation." (PMID 36551532, 2022). "Immunohistochemistry was conducted on tumor tissues from BC patients, and ADRM1 protein levels were assessed and scored in both tumor and adjacent non-tumor tissues." (PMID 37684377, 2023). "In both groups (Fra-2 cl 1 and cl 2), some interesting genes could be identified, e.g., in the Fra-2 cl 1 primary tumours LGALS1, ADRM1, and CTTN, which were upregulated and LUM (Lumican), MAN1A1, and SPARC, which were significantly downregulated." (PMID 34693476, 2022).
ADRM1 also shares sentences with these, for which no sentence is quoted: colorectal cancer (4 papers); colon carcinoma (3); ovarian tumors (2); adenoma (1); autoimmune disease (1); Azoospermia (1); Bardet-Biedl syndrome (1); COVID-19 (1); diffuse large B-cell lymphoma (1); fallopian tube cancer (1); hepatitis B virus infection (1); infertile (1); intrahepatic cholangiocarcinoma (1); lung adenocarcinoma (1); non-small cell lung carcinoma (1); pancreatic adenocarcinoma (1); pheochromocytoma (1); reproductive diseases (1); seminoma (1); thymoma (1).